NPM1 (nucleophosmin 1)
Diseases named in the same sentence as NPM1 in open-access papers (continued):
Sharing a sentence is not in itself a finding about the gene and the disease.
acute myeloid leukemia (continued). "In the study of acute myeloid leukemia (AML), it was found that FTO can upregulate proteins such as PML-RARA and NPM1 to promote the occurrence and development of leukemia." (PMID 39820532, 2025). "For younger, medically fit patients with NPM1-mutated, FLT3-wildtype acute myeloid leukemia (AML) intensive chemotherapy represents standard of care (SOC), with complete remission (CR) rates observed in up to 85% of patients and 5-year overall survival (OS) rates of 40–50%." (PMID 40629154, 2025). "At the same time, other genetic alterations commonly found in acute myeloid leukemia, like DNMT3, TET2, NPM1, IDH1 or IDH2, are rarely detected, confirming the unique pathogenesis of APL." (PMID 38921185, 2024). "Menin is also critical in regulating genes that drive cancer growth in acute myeloid leukemia (AML), and more recently, targeting menin’s interaction with KMT2A has emerged as a promising therapeutic strategy for treating AML, especially with KMT2A rearrangement and NPM1 mutations." (PMID 39594699, 2024). "Nucleophosmin‐1 (NPM1) mutations in acute myeloid leukemia (AML) confer a survival advantage in the absence of FLT3‐internal tandem duplication (FLT3‐ITD)." (PMID 35048553, 2022). "However, arsenic trioxide (As2O3) has recently shown significant efficacy in patients with acute promyelocytic leukemia (APL) and many other malignancies, such as adult T-cell leukemia/lymphoma (ATL) and NPM1 mutant acute myeloid leukemia (AML)." (PMID 34887747, 2021). "We extracted expression profiles of the seven genes of interest (C-Myc, NPM1, NCL, FBL, NHP2L1, NOP56 and NOP58) determined by RNA-seq of AML samples from the TCGA dataset (TCGA Research Network, Acute Myeloid Leukemia dataset)." (PMID 28103300, 2017). "However, similar to NPM1 and FLT3 mutations in acute myeloid leukemia (AML), SRSF2 mutations seem to occur later in the development of myeloid neoplasms than TET2 mutations." (PMID 27029036, 2016). "For acute myeloid leukemia the panel is composed of FLT3ITD/FLT3-TKD, NPM1, C-KIT, PTPN11 and CEBPA." (PMID 23863689, 2013). "NPM1 mutation in acute myeloid leukemia (AML) was first identified by the aberrant cytoplasmic localization of NPM1 protein, which is normally located in the nucleoli of non-mitotic cells." (PMID 23226219, 2012). "Prognostic markers, such as NPM1, Flt3-ITD, and cytogenetic abnormalities have made it possible to formulate aggressive treatment plans for unfavorable acute myeloid leukemia (AML)." (PMID 20416083, 2010). "Similarly, in acute myelogenous leukemia (AML), nucleophosmin 1 (NPM1) regulates PTEN nuclear exclusion by inhibiting its USP7-mediated deubiquitination." (PMID 41157055, 2025). "Moreover, common mutations in the NPM1 gene, which frequently occur in acute myeloid leukemia (AML), result in a mutated form of NPM1 that is largely absent from the nucleolus." (PMID 39036727, 2024). "PD-L1 expression level, which was determined by PCR as the ratio of transcription variants v1/v2, is an important negative prognostic factor for the acute myeloid leukemia, specifically for patients with FLT3-ITD and concomitant NPM1 mutation." (PMID 31185600, 2019).
acute myeloid leukemia (continued). "Both the World Health Organization and the European Leukemia Net classifications have included molecular markers such as NPM1, FLT3 and CEBPA as a prognostic factor for cytogenetically normal-acute myeloid leukemia (CN-AML) reinforcing their importance in cytogenetics." (PMID 23941109, 2013). "AML: acute myeloid leukemia; ALL: acute lymphoblastic leukemia; MRD: minimal residual disease; NPM1: nucleophosmin 1; FLT3: Fms-like tyrosine kinase-3; CNS: central nervous system; SCT: Stem cell transplantation; CR: complete remission." (PMID 39310608, 2024). "A 60‐year‐old woman previously diagnosed with acute myeloid leukaemia (AML) with fibrosis (normal karyotype, NPM1‐mutated, FLT3‐ITD negative, TET2 mutations (two variants) and SRSF2 mutations detected on our myeloid gene panel) presented with worsening pain and swelling in her right arm and leg." (PMID 35845279, 2021). "NPM1 mutations are commonly observed (~30%) in acute myeloid leukemia (AML), suggesting that SMYD5 participates in myeloid cell differentiation/proliferation through its interaction with NPM1." (PMID 27377701, 2016). "In our study, FLT3-ITD and NPM1 mutations were considered in the risk stratification according to NCCN Guidelines (Version 1.2015 Acute Myeloid Leukemia), we included risk stratification but not mutational status of FLT3-ITD and NPM1 as individual variables in our multivariate analysis." (PMID 27528035, 2016). "This retrospective cohort study assessed adult patients with acute myeloid leukemia (AML) who received FLT3 and/or NPM1 testing treated at any Veterans Health Administration (VHA) facility or at Vanderbilt University Medical Center (VUMC) between January 2006 and December 2016." (PMID 41332821, 2025). "RVB is classified as a pioneering menin inhibitor and is currently being developed to treat relapsed or refractory (R/R) KMT2A-rearranged acute leukemias, which include both acute myeloid leukemia (AML) and acute lymphoblastic leukemia (ALL), as well as NPM1-mutant AML." (PMID 39768795, 2024). "KO-539 induces complete remission (CR) in two out of six patients with relapsed/refractory acute myeloid leukemia (R/R AML), including a minimal residual disease (MRD)-negative CR in a NPM1-mutated AML patient co-mutated for DNMT3A and KMT2D." (PMID 38255885, 2024). "Interestingly, genetic alterations commonly found in acute myeloid leukemia like DNMT3, TET2, NPM1, IDH1 or IDH2 are rarely detected, suggesting that PML-RARA exhibits a distinct transformation pathway among AML." (PMID 32295268, 2020). "Given that, in acute myeloid leukemia, NPM1 physically binds to FOXM1 via the portion of NPM1 that is not retained in the NPM-ALK fusion." (PMID 31390744, 2019).
leukemia (229 papers, 2010 to 2026). A malignant (clonal) hematologic disorder, involving hematopoietic stem cells and characterized by the presence of primitive or atypical myeloid or lymphoid cells in the bone marrow and the blood. "Of note, the first Menin inhibitor, Revumenib, was approved for the treatment of relapsed and refractory leukemia with KMT2A‐rearrangements or NPM1 mutations in November 2024." (PMID 40181550, 2026). "NPM1-mutated leukemia is generally associated with favorable patient outcomes and improved treatment response." (PMID 41413654, 2026). "Menin inhibitors represent novel drugs with astonishing clinical activity against NPM1‐mutated or KMT2A‐rearranged leukemia in patients suffering from relapsed or refractory disease." (PMID 39887730, 2026). "In fact, many key molecular features that had been described in the context of KMT2A‐fusion proteins are highly similar to those observed in NPM1‐mutated leukemias." (PMID 39887730, 2026). "Although NPM1 is normally confined to the nucleolus, mutant forms commonly observed in AML are aberrantly localized to the cytoplasm, a defining feature of NPM1-mutated leukemias." (PMID 40973767, 2025). "In 2011, these results provided initial insights showing that mutant NPM1, in co-operation with other secondary mutations, drives leukemia initiation and progression in mice." (PMID 40647396, 2025). "A recent study has demonstrated the in vitro efficacy of DS-1594b as monotherapy or in combination with Venetoclax in KMT2A-r and NPM1-mutation cell lines, as well as in primary leukemia samples." (PMID 40361241, 2025). "NPM1 mutation-specific CD8+ T cells can directly lyse leukemia cells harboring NPM1 mutations, whereas CD4+ T cells support CD8+ T cell function and induce HLA class II-mediated anti-tumor cytotoxic responses." (PMID 40861464, 2025). "NPM1 mutations in AML define a distinct leukemia entity [WHO classification 2022 and ICC 2022: AML-defining recurrent genetic abnormalities], can act as founder mutations that are stable over the course of disease, and are not expressed in normal tissue." (PMID 40557158, 2025). "Patients harboring NPM1 mutations are diagnosed as having NPM1-mutated AMLs, which are types of leukemia with distinct clinical and laboratory characteristics." (PMID 40647396, 2025). "Preclinical studies have supported the efficacy of Menin inhibitors in both MLL-rearranged and NPM1-mutated models of leukemia." (PMID 40227641, 2025). "Mutated NPM1 is a driver gene that is essential for malignant transformation early in the development of leukemia." (PMID 40557158, 2025). "On-label use of revumenib in KMT2A-rearranged leukemia and late-phase trials of both agents in NPM1-mutated disease have shifted the field toward combination strategies in frontline and salvage settings." (PMID 41347170, 2025). "Our study evaluated MRD by MFC, which is not as sensitive as deeper qPCR based assays standardly used core binding factor leukemia, NPM1-mutated AML, and acute promyelocytic leukemia." (PMID 39695333, 2025). "In comparison to APL with PML::RARA, APL-like AML with NPM1 mutation exhibits leukemia cells with lower SSC, frequent expression of CD4, and higher white blood cell counts." (PMID 39432585, 2024). "While the leukemia initiating function of the NPM1 mutation is clearly dependent on HOX activity, the favorable treatment responses in these patients with upregulation of HOX cluster genes is a poorly understood paradoxical observation." (PMID 38453907, 2024). "NPM1-mutated AML is a specific leukemia type characterized by the disturbance of nuclear–cytoplasmic transport." (PMID 39336484, 2024). "Another study identified a leukemia-associated immunophenotype (LAIP) of CD25+/CD34+/CD99+/CD123+ that is strictly associated with FLT3 ITD in AML with NPM1 mutation and a normal karyotype." (PMID 39594810, 2024).
leukemia (continued). "The ELN also stipulates suitable molecular biomarkers, highlighting leukemia initiating variants (e.g., NPM1, CBFB::MYH11, RUNX1::RUNX1T1, PML::RARA) essential in disease monitoring." (PMID 38891959, 2024). "These systems not only reveal morphological features but also predict the mutation status of genes in leukemia, such as the NPM1 mutation, common in AML." (PMID 39574909, 2024). "This inhibitor, TDI-11055, completely blocked disease progression in MLL-rearranged and NPM1-mutated leukemia models through disrupting key oncogenic transcriptional programs that these tumors depend on." (PMID 38914477, 2024). "AML is a heterogeneous disease with regard to leukemia-associated genetic abnormalities, and one of the most common abnormalities is insertions in the NPM1 gene (referred to as NPM1-Ins)." (PMID 38791118, 2024). "Menin inhibitors have been studied in early-phase clinical trials of KMT2A-rearranged or NPM1-mutated leukemia, with MEN1 mutations implicated in resistance mechanisms." (PMID 38571944, 2024). "Aberrant expression of HOX and MEIS1 family genes, as seen in KMT2A-rearranged, NUP98-rearranged, or NPM1-mutated leukemias leads to arrested differentiation and leukemia development." (PMID 39179671, 2024). "Menin inhibitors show significant clinical efficacy against KMT2A-rearranged and NPM1-mutated acute leukemias, with promising potential to address unmet needs in various pediatric leukemia subtypes." (PMID 39179671, 2024). "Nucleophosmin 1 (NPM1) is one of the commonly mutated genes and is found in approximately 30% of adult leukemia cases." (PMID 36831522, 2023). "To clarify the role of TP53INP2 in the autophagy process of NPM1-mutated leukemia cells, we first silenced TP53INP2 to observe the changes in autophagic level." (PMID 36675134, 2023). "Of course, further work is necessitated to clarify the role of TP53INP2-mediated autophagy in mouse knock-in models that mimic human NPM1-mutated leukemia." (PMID 36675134, 2023). "Preclinical studies showed that menin inhibition downregulates HOX and MEIS1 transcription and reverses leukaemogenesis in KMT2Ar-r- or NPM1-mutated leukaemia models." (PMID 36922593, 2023). "Here, we used bioinformatics analysis to screen out the autophagy-associated dysregulated gene TP53INP2 in NPM1-mutated leukemia." (PMID 36675134, 2023). "To further determine the TP53INP2 expression in NPM1-mutated leukemia, we acquired the RNA-seq data of TP53INP2 in a group of leukemia-lymphoma cell lines in the CCLE database." (PMID 36675134, 2023). "The results showed that TP53INP2 was dramatically upregulated in NPM1-mutated leukemia patients (n = 21) compared with NPM1-unmutated leukemia patients (n = 18)." (PMID 36675134, 2023). "T cells were expanded or primed from patient or donor peripheral blood mononuclear cells by NPM1-mutated protein-derived peptides, and tested for leukemia antigen-targeted cytotoxic activity, cytokine production and hematopoietic precursor inhibitory effect." (PMID 37345068, 2023). "Next, we explored the molecular mechanism underlying the high expression of TP53INP2 in NPM1-mutated leukemia cells." (PMID 36675134, 2023). "In the case of NPM1mut-specific products, immune escape is more unlikely, as NPM1 mutation is a driver of genetic lesion, critical for leukemia cell survival." (PMID 37345068, 2023). "The study group of Issa and colleagues performed the first clinical trial with the menin inhibitor revumenib in subjects affected by leukemia harboring a rearranged KMT2A or mutated NPM1." (PMID 37816719, 2023). "Followingly, we looked into the reason that TP53INP2 is largely located in the cytoplasm of NPM1-mutated leukemia cells." (PMID 36675134, 2023).
leukemia (continued). "In the current study, we first utilized bioinformatics analysis to ascertain the dysregulated genes associated with autophagy in NPM1-mutated leukemia and obtained three genes including TUSC1, NKX2-3, and TP53INP2." (PMID 36675134, 2023). "NPM1 mutations correlate with most mature stages of leukemia arrest together with TET2 or IDH mutations in granulocyte progenitors-like AML or with DNMT3A mutations in monocyte progenitors-like AML." (PMID 35973983, 2022). "Based on these promising preclinical data, development has moved into clinical trials focusing on KMT2Ar and NPM1 mutated leukemias." (PMID 36497385, 2022). "The Armstrong lab demonstrated that NPM1 mutant leukemia is dependent on menin binding to wild type KMT2A and loss of KMT2A-menin abrogates the leukemogenic effect of NPM1 mutations." (PMID 36497385, 2022). "It was reported that menin-MLL1 inhibition combined with venetoclax demonstrated anti-leukemia activity in primary NPM1-mutated AML samples." (PMID 36237321, 2022). "Several clinical studies are recruiting to assess the safety and efficacy of menin inhibitors such as SNDX-5613 and KO-539 on leukemia with MLL-rearrangement or NPM1 mutation (NCT04067336, NCT04065399, NCT04811560, NCT04752163)." (PMID 36237321, 2022). "More recently, the anti-PD-1 antibody, nivolumab, was found to increase leukemia-associated antigen-stimulated cytotoxic T cells and cytotoxicity against stem cell-like cells, especially those carrying NPM1 mutations." (PMID 36008542, 2022). "Conversely, leukemia-specific antigens deriving from altered proteins encoded by leukemogenic mutations (e.g., NPM1), are specifically expressed in malignant clones and therefore represent ideal targets." (PMID 36008542, 2022). "ATO and venetoclax synergistically induces the apoptosis of NPM1-mutated OCI-AML3 cells in vitro and showed anti-leukemia activity in two relapsed and/or refractory (R/R) NPM1-mutated AML patients." (PMID 36237321, 2022). "Expression of FLT3-TKD is insufficient to trigger leukemia in mice; however, a co-NPM1 mutation actively led to the onset of AML in mice." (PMID 33836835, 2021). "Exceptions are AML with specific cytogenetic abnormalities or nucleophosmin 1 (NPM1) mutated leukemias." (PMID 33917307, 2021). "(v) A further proof that NPM1 mutations harbor leukemia-initiating properties is the high reappearance rate of NPM1 in relapse, which was demonstrated as high as 86–100% in several clinical observations." (PMID 34153064, 2021). "To investigate the potential mechanisms by which HOTAIRM1 contributes to the malignant phenotypes of NPM1-mutated leukemia cells, we examined its subcellular localization." (PMID 34615546, 2021). "VTP50469 is a potent and specific inhibitor of the Menin/KMT2A interaction with demonstrated activity against KMT2A-fusion leukemia and NPM1-mutated leukemia, where it targets wild-type KMT2A." (PMID 33542482, 2021). "Despite our improved understanding of NPM1 mutations and their consequences, the underlying leukemia pathogenesis is still unclear." (PMID 32545659, 2020). "Our knowledge on the aberrant function of NPM1 mutations which lead to a unique leukemia has expanded." (PMID 32545659, 2020). "The analysis of clonal dynamics in NPM1-mutated AMLs allowed to show the clonal heterogeneity and to propose a model of mutational development of these leukemias." (PMID 30813354, 2019). "Recent outcomes have revealed that abnormal increased cytoplasmic localization of PML appears in NPM1-mutated leukemia cells." (PMID 31777586, 2019). "Nucleophosmin(NPM1)-mutated protein, a leukemia-specific antigen, represents an ideal target for AML immunotherapy." (PMID 30783516, 2019).